LGALS1 (galectin 1)
Diseases named in the same sentence as LGALS1 in open-access papers (continued):
Sharing a sentence is not in itself a finding about the gene and the disease.
type 2 diabetes (5 papers, 2022 to 2026). "In a linear regression model adjusting for age, sex, BMI, HOMA2-IR, HOMA2-B and HbA1c, there was a significant inverse association between galectin-1 levels and eGFR among individuals with type 2 diabetes at the time of diagnosis (p = 0.001)." (PMID 34743218, 2022). "Galectin-1 was independently and inversely associated with type 2 diabetes and glucose and positively associated with age, BMI, metabolic and inflammatory markers." (PMID 36295832, 2022). "Further, the prospective analyses suggested a positive association between galectin-1 levels at baseline and incidence of type 2 diabetes, independently of established risk factors." (PMID 34743218, 2022). "Furthermore, galectin-1 was associated with increased risk of type 2 diabetes after age and sex adjustment (HR 1.30 per SD increase; 95% CI 1.19, 1.43; p = 1.4 × 10−8)." (PMID 34743218, 2022). "However, galectin-1 was associated with increased risk of type 2 diabetes (per SD increase, HR 1.12; 95% CI 1.02, 1.24)." (PMID 34743218, 2022). "Studies with similar populations reveal increased levels of galectin-1 in obese and type 2 diabetes populations, which correlate positively with body mass index and hyperinsulinemia." (PMID 41590667, 2026). "An unbiased proteomic analysis of adipose tissue interstitial fluid in patients with type 2 diabetes (T2D) and healthy controls reported elevated galectin-1 levels in T2D." (PMID 38777863, 2024). "We found that galectin-1 levels were higher in the SIRD group (compared with other type 2 diabetes subgroups), and, among individuals with SIRD, higher galectin-1 levels were cross-sectionally associated with lower eGFR." (PMID 34743218, 2022). "Conversely, we have previously reported that there is an inverse relationship between galectin-1 and type 2 diabetes when adjusting for BMI." (PMID 34743218, 2022). "MR analyses of the effect of galectin-1 among the four subgroups of type 2 diabetes showed that, among the SIRD group, genetically elevated levels of galectin-1 were positively associated with eGFR (p = 5.7 × 10−3)." (PMID 34743218, 2022). "This is to the best of our knowledge the first large, population-based cohort study examining the longitudinal association of galectin-1 with CKD and type 2 diabetes." (PMID 34743218, 2022). "Of note, there is a higher prevalence of heredity for type 2 diabetes in individuals with low galectin-1 levels." (PMID 36295832, 2022). "We have also observed a strong cross-sectional association between circulating levels of galectin-1 and several markers of the metabolic syndrome in a population-based cohort, but BMI-adjusted galectin-1 levels were lower in individuals with type 2 diabetes." (PMID 34743218, 2022). "The associations of baseline galectin-1 with incident CKD and type 2 diabetes were assessed with Cox regression, adjusting for established risk factors." (PMID 34743218, 2022). "Individuals with SIRD were selected on two factors related to galectin-1, both type 2 diabetes and propensity for kidney disease; thus, collider bias could potentially be introduced in the MR analyses conducted within the ANDIS cohort." (PMID 34743218, 2022). "Using the large, population-based Malmö Diet and Cancer Study–Cardiovascular Cohort (MDCS-CC), we aimed to examine whether circulating galectin-1 levels associate with incident CKD and type 2 diabetes, independently of established risk factors." (PMID 34743218, 2022). "Future studies are needed to explore the mechanisms by which galectin-1 affects kidney function and whether it could be a useful target for improving kidney function among individuals with type 2 diabetes." (PMID 34743218, 2022). "Interestingly, in previous studies, we have measured higher galectin-1 levels in the subcutaneous interstitial fluid, but similar serum levels, in individuals with type 2 diabetes compared with healthy control participants." (PMID 34743218, 2022).
type 2 diabetes (continued). "Including galectin-1 in addition to established risk factors did not improve model discrimination of CKD or type 2 diabetes." (PMID 34743218, 2022). "Future studies are needed to explore the mechanisms by which galectin-1 affects kidney function and whether it could be a useful target among individuals with type 2 diabetes for renal improvement." (PMID 34743218, 2022). "However, MR results did not provide evidence for a causal effect of galectin-1 levels on incidence of type 2 diabetes." (PMID 34743218, 2022). "Galectin-1 gene expression has been shown to be increased in adipocytes from obese mice, and in isolated adipocytes from type 2 diabetes patients (T2D)." (PMID 36295832, 2022). "Two-sample MR analyses could not ascertain a causal effect of galectin-1 on CKD (OR 0.92; 95% CI 0.82, 1.02) or type 2 diabetes (OR 1.05; 95% CI 0.98, 1.14) in a general population." (PMID 34743218, 2022).
anemia (4 papers, 2017 to 2023). A reduction in the number of red blood cells, the amount of hemoglobin, and/or the volume of packed red blood cells. "Revelation of positive correlation between systemic IL-1, IL-33 and galectin-1 levels in serum of anemic CRC patients suggested on synergistic effect of these cytokines in pathogenesis of anemia in CRC patients." (PMID 35611243, 2022). "In the periphery, increased ROS further contribute to anemia and secreted factors such as galectin-1 have a yet to be elucidated role in modulating erythropoiesis." (PMID 29922180, 2018). "Presented data revealed higher Galectin-1, IL-1 and IL-33 values in serum of CRC patients with anemia, establishing them as new players in genesis and progression of anemia of inflammation." (PMID 35611243, 2022). "Predomination of Galectin-1, IL-1 and IL-33 in anemic CRC patients implicates on their potential role in anemia genesis and further development." (PMID 35611243, 2022). "In our study, we showed that patients with CRC and detected anemia had significantly higher level of systemic Galectin-1 compared to the group of CRC patients without anemia." (PMID 35611243, 2022). "Concentrations of IL-33, Galectin-1 and IL-1 have been studied in blood samples of 55 CRC patients (27 without anemia and 28 with anemia)." (PMID 35611243, 2022).
atherosclerosis (4 papers, 2020 to 2025). A disease characterized by the build-up of fatty material and calcium deposition in the arterial wall resulting in partial or complete occlusion of the arterial lumen. "They reported that 29 proteins, including Heat Shock Protein 70, lymphocyte-specific protein phosphatase, α-enolase, and galectin-1, had potential as biomarkers of atherosclerosis-preventive activities induced by soy isoflavone consumption." (PMID 39336514, 2024). "Our findings, in agreement with previous reports, support the role of galectin-1 in vascular inflammation and atherosclerosis in patients with CAD." (PMID 33244142, 2020). "Instead of a potent antioxidant acting against vascular inflammation, galectin-1 is more likely to be a mediator involved in the development of atherosclerosis in chronic CAD." (PMID 33244142, 2020). "Galectin-1 (Gal-1) is a galactoside-binding protein that may serve as a new target for the treatment of atherosclerosis." (PMID 36552822, 2022). "Another possible explanation is that galectin-1 is an early-stage byproduct of atherosclerosis." (PMID 33244142, 2020).
Autoimmunity (4 papers, 2014 to 2024). The occurrence of an immune reaction against the organism's own cells or tissues. "Galectin-1 (LGALS1) is a carbohydrate-binding protein that plays key immune regulatory roles in autoimmunity and chronic inflammation." (PMID 38703299, 2024). "With respect to promoting Treg activity, the lectin galectin-1 (Gal1) has been shown to ameliorate inflammation in animal models of autoimmunity by sparing Tregs and Th2 cells while promoting apoptosis in Th1, Th17, and Tc1 cells." (PMID 29463785, 2018). "In fact, Lgals1-/- mice have Foxp3+ Treg cell suppressive dysfunction and are prone to autoimmunity." (PMID 30319642, 2018).
bladder tumors (4 papers, 2019 to 2022). "They demonstrated the ability of PorGal8 to preferentially accumulate in tumor tissues in a xenograft bladder tumor model, which includes mice with UM-UC-3 cells (containing high levels of galectin-1)." (PMID 36195918, 2022). "While 18F-labeled galactodendritic unit 4 binds to and accumulates in galectin-1–overexpressing UMUC3 bladder tumors, the glucose radiotracer 18F-FDG is reabsorbed after intravesical administration and accumulates in the kidneys and heart." (PMID 32005776, 2020). "The 18F-labeled galactodendritic unit 4 offers the ability to interact with galectin-1, resulting in a high ability to accumulate and image galectin-1–overexpressing bladder tumors." (PMID 32005776, 2020). "Galectin-1 protein is known to be overexpressed in many tumor tissues (e.g., bladder tumors)." (PMID 36195918, 2022).
brain ischemia (4 papers, 2011 to 2020). Diminished or absent blood supply to the brain caused by obstruction (thrombosis or embolism) of an artery resulting in neurologic damage. "Galectin-1 administration reduced apoptosis of neurons, decreased brain infarction volume and improved neurological function induced by brain ischemia." (PMID 31156388, 2019). "Recent studies from our group have shown that Galectin-1 has therapeutic potential for treating neurodegenerative disorders (i.e., brain ischemia and spinal cord injury) via its ability to modulate neurogenesis." (PMID 21269521, 2011). "Astrocyte galectin-1 has been associated with worsening neurodegeneration of motor neurons in an ALS mouse model, but with neurotrophic and anti-inflammatory effects in models of MS and brain ischemia." (PMID 32736565, 2020). "Galectin-1(Gal1) is expressed around infarcted tissue after brain ischemia." (PMID 21951913, 2011). "This Galectin-1 function is crucial for functional recovery after brain ischemia." (PMID 21269521, 2011).
brain tumor (4 papers, 2012 to 2025). "Studies investigating the targeting of galectin-1 for radioresistance are encouraged in an effort to treat this aggressive brain tumor." (PMID 29378529, 2018). "We assessed the survival of nude mice harboring xenograft brain tumors induced by a few of our U87 galectin-1 clones." (PMID 22583806, 2012). "Studies report that galectin-1 regulates angiogenesis-related genes via RNA binding, while its complex formation with HOXA5 reprograms transcriptional networks in brain tumor stem cells." (PMID 40863614, 2025).
chronic myelogenous leukemia (4 papers, 2012 to 2022). "We first tested GM-CT-01 on K562, a chronic myeloid leukemia cell line that constitutively produces both endogenous Galectin-3 and Galectin-1." (PMID 36430839, 2022). "In the case of LGALS1, a recent report characterized the induction of resistance to a variety of anticancer drugs following ectopic expression of galectin-3 in chronic myelogenous leukemia cells." (PMID 22848499, 2012). "Moreover, we provided the first data showing that NF-κB translocation induced by P38 MAPK activation was responsible for the modulation effect of galectin-1 on MDR1 in the chronic myelogenous leukemia cells." (PMID 27050374, 2016).
esophageal squamous cell carcinoma (4 papers, 2021 to 2022). Esophageal squamous cell carcinoma (ESCC) is a type of esophageal carcinoma (EC) that can affect any part of the esophagus, but is usually located in the upper or middle third. "We found that galectins have been mainly studied in the context of esophageal squamous cell carcinoma and that galectin-1, -3, and -9 expression are most frequently reported." (PMID 36497271, 2022). "However, the prognostic significance of galectin-1 expression in patients with locally advanced esophageal squamous cell carcinoma (ESCC) treated with chemoradiotherapy remains unknown." (PMID 34201887, 2021).
keloid (4 papers, 2010 to 2022). An irregularly shaped, elevated mark on the skin caused by deposits of excessive amounts of collagen during wound healing. "Galectin-1/3 was present in the cytoplasm and along the cell membrane of some immune cells and fibroblasts, suggesting that galectin-1/3, in concert with some of the extracellular matrix molecules, was produced to counteract the immune response in keloid." (PMID 35967426, 2022). "However, the results of the present study revealed for the first time the downregulation of five genes (ANXA1, ASPN, IGFBP7, LGALS1, and PTN) which is in contrast to the upregulation of the same genes in African and Caucasian keloid samples." (PMID 32085797, 2020). "A statistically significant (P < .05) differential expression and a fold change of more than 2 were determined between keloid margin and internal control biopsy samples for 10 genes, including ACAN, ASPN, C5orf13, HIF1A, IGFBP7, INHBA, LGALS1, PTN, SERPINH1, and TNFAIP6." (PMID 20418938, 2010).
liver fibrosis (4 papers, 2017 to 2024). "In particular, a recent study found that empagliflozin suppresses liver fibrosis by regulating different pathways (Galectin-1/Neuropilin-1) related to LSEC and HSC communication." (PMID 38534382, 2024). "A recent report showed that the interaction of galectin-1 with neuropilin-1 promotes liver fibrosis by activating the hepatic stellate cells." (PMID 33431823, 2021).
malignant glioma (4 papers, 2019 to 2023). A grade III or grade IV glioma arising from the central nervous system. "Herein, the expression of FAM289 was positively correlated with Galectn-1, suggesting that FAM289 can be used in association with Galectin-1 as a complementary diagnostic tool to improve discrimination between benign and malignant gliomas." (PMID 31492191, 2019). "FAM289 contributes to tumor progression in malignant glioma by interacting with Galectin-1 thereby promoting FAM289 protein translocation into the cell nucleus." (PMID 31492191, 2019). "We demonstrated for the first time that FAM289 contributes to tumorigenesis in malignant gliomas by interacting with Galectin-1 to promote FAM289 protein into the cell nucleus." (PMID 31492191, 2019). "Recently, single-sample gene set enrichment analysis showed that, in malignant gliomas with the poorest prognosis, LGALS1—which encodes galectin-1, a β-galactoside-binding protein with immunosuppressive characteristics—is highly upregulated in association with PTEN and EGFR mutations." (PMID 33396284, 2020). "Nuclear FAM289-Galectin-1 interaction controls the activation of the ERK pathway to upregulate DNMTs expression and the tumor-promotion effects of FAM289 in malignant glioma." (PMID 31492191, 2019).
mesothelioma (4 papers, 2016 to 2023). A usually malignant and aggressive neoplasm of the mesothelium which is often associated with exposure to asbestos. "We found higher expression of LGALS1 in three of the four mesothelioma PEs and in some cancer-PEs, but higher LGALS1 levels are more prominent in the infectious PEs." (PMID 35197508, 2022). "Strikingly, IRF3 and LGALS1 (Galectin-1) genes were highly expressed in both murine and human mesothelioma cells." (PMID 34768716, 2021). "Correlation of IRF3 with the immune checkpoints in TCGA MESO and coexpression with LGALS1 in scRNA-Seq data from our patient samples imply that IRF3 may be an inhibitory transcription regulator in mesothelioma." (PMID 34768716, 2021). "IRF3 expression and the immune checkpoint genes significantly correlated with LAG3 and LGALS1 (Galectin) genes expression in mesothelioma cells, while positive correlation was found between IRF3 and HAVCR2 (TIM-3) or PDCD1LG2 (PD-L2) expression in monocytes/macrophages." (PMID 34768716, 2021).
metabolic syndrome (4 papers, 2022 to 2026). A cluster of metabolic risk factors for CARDIOVASCULAR DISEASES and TYPE 2 DIABETES MELLITUS. "We demonstrate that cross-sectionally circulating galectin-1 levels are strongly inversely associated with eGFR as a measure of kidney function and several quantitative traits defining the metabolic syndrome." (PMID 34743218, 2022). "The study found that participants with the most severe degree of metabolic syndrome had the lowest circulating galectin-1 levels, which was also associated with a more severe inflammatory condition." (PMID 36295832, 2022). "In agreement with earlier epidemiological studies, BMI and related clinical markers of the metabolic syndrome correlated with circulating galectin-1 levels in our study." (PMID 34743218, 2022). "The enhanced inflammation in UC-patients in the terminal phase of the metabolic syndrome may be due to a decreased immunomodulatory influence of galectin-1." (PMID 36295832, 2022).
oral cancer (4 papers, 2020 to 2025). "In addition, it was found that LGALS1 was linked to oral cancer progression and metastasis and potentially regarded as a prognostic biomarker for oral cancer therapy." (PMID 35003322, 2021). "Outside of the breast, LGALS1 is linked to invasiveness and metastasis in oral cancer." (PMID 32457901, 2020).
papillary thyroid carcinoma (4 papers, 2010 to 2025). "Galectin-1 IHC expression was significantly associated with tumor size of papillary carcinoma cases (P = 0.002)." (PMID 41480246, 2025). "Galectin-1 IHC staining in papillary carcinoma: 62.2% (23/37) of cases were positively stained, 37.8% (14/37) of cases were negative." (PMID 41480246, 2025). "The current study results show that all 16.2% (6/37) cases of papillary carcinoma with lymph node metastases are positively stained for galectin-1 (100%)." (PMID 41480246, 2025). "There was a significant difference in IHC of galectin-1 in papillary carcinoma between different tumor sizes, where all cases that were ≥4 cm (100%) showed expression for galectin-1 (P value, 0.002)." (PMID 41480246, 2025).
parasite infection (4 papers, 2015 to 2023). "Within the context of a wider Th2 environment of the type established during parasite infection, galectin-1 and -2 have been shown to inhibit Th1 cytokine release from T cells and promote Th2 cytokine release." (PMID 29659599, 2018). "Together, our findings provide new information on the roles of galectin-1 during parasitic infection and indicate an important role for this molecule in tissue-specific Th1 cell development, but not CD4+ T cell IL-10 production." (PMID 29075269, 2017). "Lgals1-/- mice infected with T. cruzi Tulahuén strain showed higher parasitemia together with lower survival rate, which was more evident in female than male animals." (PMID 26451839, 2015). "In parasitic infections, galectin-1 usually plays a pro-infection role." (PMID 37047471, 2023). "To determine whether similar mechanisms of galectin-1-mediated immune regulation influenced disease outcome in another important parasitic disease, we infected Lgals1−/− mice and WT controls with L. donovani and assessed control of parasite growth and associated immune responses." (PMID 29075269, 2017). "Our results highlight the role of Gal–1 in the complex parasite-driven immune-endocrine networks since important discrepancies in parasitemia and survival rates were observed in male and female animals lacking the Lgals1 gene." (PMID 26451839, 2015). "The density of parasitized cells was significantly higher in the heart, but not in the skeletal muscle of Lgals1-/- mice infected with T. cruzi Tulahuén strain at the peak of parasitemia, compared with WT mice; this effect was independent of the gender of the mice (p<0.05)." (PMID 26451839, 2015). "Interestingly, Lgals1-/- mice infected with trypomastigote of the Tulahuén strain had significantly higher parasitemias compared to WT mice (p<0.05), regardless of the gender of the animals." (PMID 26451839, 2015).